FGF4 (fibroblast growth factor 4)
Diseases named in the same sentence as FGF4 in open-access papers (continued):
Sharing a sentence is not in itself a finding about the gene and the disease.
Hallux valgus (1 paper, 2021). Lateral deviation of the great toe (i.e., in the direction of the little toe). "Then we examined the mRNA levels of FGF family, FGF1, FGF4, FGF7, FGF8, FGF9 and found the high mRNA level of FGF9 in hallux valgus patients." (PMID 33456347, 2021).
Hypertension (1 paper, 2022). The presence of chronic increased pressure in the systemic arterial system. "Overall, SNPs related to height were the most common, and no genetic variant of the FGF4 gene was related to hypertension." (PMID 35980984, 2022).
Kaposi's sarcoma (1 paper, 2021). A malignant neoplasm characterized by a vascular proliferation which usually contains blunt endothelial cells. "In adults, FGF-4 mainly exists in tumors, such as gastric cancer, Kaposi’s sarcoma and breast cancer, and is not produced under normal physiological conditions." (PMID 34721299, 2021).
kidney damage (1 paper, 2025). "We demonstrate that endogenous FGF4 expression is significantly reduced in both murine and human renal tissues during DKD progression, with podocyte-specific knockout of Fgf4 exacerbating kidney damage." (PMID 41290710, 2025).
lung squamous cell carcinoma (1 paper, 2024). "It has been found that the amplification of FGF4 and FGF19 was five times more frequent in smokers with lung squamous cell carcinoma (LSCC)." (PMID 39590120, 2024).
malignant mesothelioma (1 paper, 2021). A malignant neoplasm of the pleura or peritoneum, arising from mesothelial cells. "Additionally, using the Proteome Profiler Array, we identified that other angiogenesis-related proteins including HGF, TGF-β1, FGF-4, NRG1-β1 are significantly upregulated in malignant mesothelioma cells, suggesting that these proteins may also have a prognostic and angiogenic role in MPM." (PMID 33562126, 2021).
melanoma (1 paper, 2019). A malignant, usually aggressive tumor composed of atypical, neoplastic melanocytes. "Genomic profiling of 23 available subjects also identified gene amplifications of cell cycle regulators (Cyclin D1, CDK4, or CDK6), fibroblast growth factors (FGF19, FGF3, and FGF4) and EMSY (a DNA repair inactivating gene) uniquely clustered in acral melanoma subjects in the study." (PMID 30642373, 2019).
nonalcoholic steatohepatitis (1 paper, 2025). "Interestingly, some studies suggest that Fibroblast Growth Factor 4 may have a protective effect against nonalcoholic steatohepatitis (NAS) by suppressing the cleavage and activation of CASP6 via the AMP-activated protein kinase (AMPK) signaling pathway." (PMID 40427707, 2025).
oral cancer (1 paper, 2023). "Finally, DMC hypo-methylation of FGF4 and the LINC00461 associated DMR were found to be the highest significant features for the delineation of oral cancer and OPMDs." (PMID 38234400, 2023).
ovarian carcinoma (1 paper, 2021). A malignant neoplasm originating from the surface ovarian epithelium. "It has been reported that co-inoculation of fibroblasts with ovarian cancer stem cells (OCSCs) in nude mouse significantly increases the tumorigenesis ability in vivo caused by an elevated expression of fibroblast growth factor 4 (FGF4) to maintain self-renewal capability in OCSCs." (PMID 33898430, 2021).
ovarian tumor (1 paper, 2017). "Histological examination and gene expression analysis of ovarian tumor tissues have shown abundant fibrous stroma formation, overexpression of fibroblast growth factor 4 (FGF4), and stem cell-associated genes in samples enriched with CSCs in the presence of fibroblasts." (PMID 28819364, 2017).
pituitary tumor (1 paper, 2018). A benign or malignant neoplasm affecting the pituitary gland. "Also, the pituitary tumors of fetal alcohol exposed rats had elevated levels of oncogenes PTTG, FGF4 and MMP-9, which are known to be upregulated in the invasive prolactinoma and pituitary carcinoma." (PMID 29769550, 2018).
pulmonary fibrosis (1 paper, 2026). Chronic progressive interstitial lung disorder characterized by the replacement of the lung tissue by connective tissue, leading to progressive dyspnea, respiratory failure, or right heart failure. "The present study showed that FGF4 relieved pulmonary fibrosis in diabetic mice by inhibiting the production of pulmonary fibrosis, as evaluated by the expression of relevant markers." (PMID 41347806, 2026).
Pulmonary hypoplasia (1 paper, 2025). "We describe three individuals from two families with thoracic dystrophy and pulmonary hypoplasia, each with homozygous missense variants in FGF4 in the receptor‐binding domain." (PMID 40259859, 2025).
Respiratory insufficiency (1 paper, 2025). "Our work suggests that homozygous variants in FGF4 may lead to a phenotype of thoracic abnormalities with respiratory insufficiency, which could prompt screening of other rare disease cohorts, or inclusion in diagnostic testing panels." (PMID 40259859, 2025).
serous ovarian cancer (1 paper, 2016). "FGF4, which binds FGFR2-IIIc with high affinity, was previously reported to be highly expressed in advanced-stage and poor-prognosis cases of serous ovarian cancer." (PMID 27677589, 2016).
squamous cell carcinoma (1 paper, 2016). A carcinoma arising from squamous epithelial cells. "Potential tumor suppressor genes, also found in other squamous cell carcinomas, have been discovered in the lost regions 2q33-q37.3 (PLCD4), 3p26.3-q11.1 (RBMS3, PLCD1, and CACNA2D3) and 11q12.2-q25 (CPT1A, CCND1, FGF4/FGF3, and PPP2R1B)." (PMID 26901676, 2016).
teratoma (1 paper, 2012). A non-seminomatous germ cell tumor characterized by the presence of various tissues which correspond to the different germinal layers (endoderm, mesoderm, and ectoderm). "We tested the teratoma formation potential of Fgf4-OE cells and found cell types from all three germ layers, suggesting that the alteration of Fgf4 expression has no overt effect on their differentiation potential." (PMID 23145002, 2012).
testicular cancer (1 paper, 2023). A primary or metastatic malignant neoplasm that affects the testis. "FGF4 supports germ cell survival/proliferation, and its expression in testicular cancer has been reported." (PMID 37048077, 2023).
type 1 diabetes (1 paper, 2026). "Fourth, while the current study employed a type 1 diabetes model, future research will use a type 2 diabetes model to evaluate the effects of FGF4." (PMID 41347806, 2026).
viral infections (1 paper, 2019). "We further evaluated whether FGF-4 expression is a general response to cell stress, viral infections, or more specific to HSV-1." (PMID 31791351, 2019).
tumor (51 papers, 1996 to 2026). "For instance, CST1, associated with tumor progression, and the fibroblast growth factor 4 (FGF4), imperative for embryonic development, both markedly upregulated in eCAFs and dCAFs, respectively." (PMID 39112478, 2024). "On the other hand, “Tissue Invasion and Metastasis”, involving 18 genes such as MUC16, FGF4, and MAP3K1, remains one of the leading causes of mortality in BC patients, emphasizing the importance of these genes in the tumor’s ability to spread to other tissues." (PMID 40136626, 2025). "FGF4 application is emerging as it has a unique role in oncogenesis, tumor progression, and resistance to anti-tumor therapy in multiple types of cancer." (PMID 41394119, 2025). "Tumor cells (EF43.fgf4) were stained with Cellbrite Green and co-cultured with BMDM in the indicated treatment." (PMID 37835464, 2023). "Binding assays to each of these cell subpopulations showed that CSSTRESAC-phage particles bound specifically to CD11b+F4/80+ macrophage; binding to tumor-isolated EF43.fgf4 cells and CD45R+ cells were at background levels." (PMID 34060472, 2021). "We next investigated the biological significance and potential therapeutic effects of CSSTRESAC in the EF43.fgf4 tumor model." (PMID 34060472, 2021). "(A) Therapeutic effect of systemic treatment of EF43.fgf4 tumor-bearing mice with soluble CSSTRESAC peptide (n = 10 each experimental cohort)." (PMID 34060472, 2021). "CSSTRESAC-AAVP-HSVtk or control AAVP lacking the targeting peptide (fd-AAVP-HSVtk) were delivered to cohorts of size-matched EF43.fgf4 tumor-bearing mice." (PMID 34060472, 2021). "The very restricted expression of FGF4 in these specific and rare tumor settings can be further confirmed by exploiting public gene expression data." (PMID 32392832, 2020). "This occurs through an intensive interplay between tumor cells and/or stromal cells and vascular cells, which involves several mediators, such as vascular endothelial growth factors (VEGFs), Fibroblast Growth Factor 4 (FGF4), and others." (PMID 32235370, 2020). "FGF4 is involved in several cellular processes including cell growth, tissue repair, tumor growth and invasion, and is also a well-known proto-oncogene." (PMID 32717834, 2020). "Among the top five most hyper-methylated promoters, FGF19 is related to HCC tumor promotion, FGF4 is related to HCC drug response, and HLX is involved in normal liver development." (PMID 28938868, 2017). "In accordance with our in vitro findings, cells with FGF4 treatment grew into larger tumor masses than control cells and cells with FGF4+BHQ treatment." (PMID 27677589, 2016). "Immunohistochemical analyses showed that tumor sections from FGF4-stimulated cells exhibited a marked increase in Orai1 whereas tumor sections from control and FGF4+BHQ-stimulated cells revealed no or weak staining." (PMID 27677589, 2016). "Another possible explanation is the common function of the simultaneously amplified genes of 11q13 (CTTN, FADD, CCND1, and FGF4) in tumor growth and invasion." (PMID 26194878, 2015). "Studies have demonstrated that undifferentiated NT2 cells, after RA treatment decrease their proliferation rate with a decrease of both TGF-α and FGF-4 along with a reduction in both tumor formation and the generation of new tumors in a-timic mice." (PMID 23585910, 2013). "Other studies provide some understanding of the central role of retinoic acid regulation of differentiation and suppression of tumor genes, such as FGF-4 and TGF-α, in RA-sensitive cell lines, such as the hNT2." (PMID 22619713, 2012). "MMTV integration near the Wnt1/Wnt10b and Fgf3/Fgf4 loci can lead to the expression in the same tumor of one or the other or both genes in these clusters." (PMID 23131872, 2012). "Both AGM-1470 and PPS inhibited tumour growth in otherwise untreated or tamoxifen-treated mice injected with either FGF- or FGF-4-transfected MCF-7 cells." (PMID 8624263, 1996).
tumor (continued). "We identified potential oncogenes, including Igf2, Hras, Fgf3, Fgf4, and Ccnd1 in this amplicon that could promote tumor growth in mBT0309." (PMID 41568176, 2026). "Immunofluorescence in liver-infiltrating tumor tissues showed that AAV-SHH or AAV-FGF4 successfully activated the positive feedback regulation between FGF4/SHH and GREM1 in macrophages (F4/80+), which contributed to an increase in CD206+F4/80+ macrophages and a decline in CD8+CD3+ T cells." (PMID 40849639, 2025). "Additionally, our patient’s tumor harbored several other genetic alterations, including a frameshift mutation in PTEN and copy number amplification of the MDM2 and FGF4 genes." (PMID 39590120, 2024). "In vivo, AAP/NAC inhibited tumor growth in EF43.fgf4 and 4T1 triple-negative breast tumors." (PMID 37835464, 2023). "Amongst the novel BMP4 targets identified were the transcript encoding the dual histone demethylase, KDM7A, previously shown to promote tumour growth and mediate androgen receptor activity, and FGF4; both were upregulated in both cell lines following BMP4 stimulation." (PMID 37048077, 2023). "Of these tumours, SDH-deficient (characterized by the loss of SDHB) and quadruple WT GIST (KIT/PDGFRA/SDH/RAS-P WT) subgroups were reported to display a marked overexpression of FGF4, identifying a putative common therapeutic target for the first time." (PMID 33199729, 2020). "Kitajewski’s group showed that in mammary gland tumor murine model, in which Jagged1 tumor expression was upregulated by ectopic expression of FGF4, Notch inhibition through Notch1 decoy disrupted tumor angiogenesis and delayed the growth of murine Mm5MT xenografts." (PMID 30154786, 2018). "Interestingly, we observed differences in FGF4 expression within tumors, with strong FGF4 expression observed in tumor cells located close to stroma." (PMID 27677589, 2016). "In addition, whether the regulation of CAF-exo in PMN formation and distant metastasis through the GREM1/SHH/FGF4 axis can similarly influence orthotopic tumor properties to promote the distant metastasis needs to be further investigated." (PMID 40849639, 2025). "Mouse experiments also indicated that FGF4 treatment may induce tumor metastasis." (PMID 27677589, 2016). "Ectopic expression of SHH or FGF4 activated GREM1/FGF4/SHH signaling and rescued the anti-tumor effects of GREM1 knockdown in vivo." (PMID 40849639, 2025). "It has been reported that in thyroid epithelial cells, FGFR2-IIIb reduces the expression of FGF7 and increases the ratio of FGF4/FGF7 and couples epithelial signalling with expansion of stomal to favour tumour growth." (PMID 35459137, 2022). "The upregulated gene set also included known genes related to pluripotency and growth, such as KLF5, FGF4 and GDF3, and 8 downregulated genes were known tumor suppressors." (PMID 28837588, 2017). "Both hNT2.17 and hNT2.19 cell lines downregulate their expression of the tumor-proteins TGF-α and FGF-4 with RA exposure and differentiation in vitro." (PMID 22619713, 2012). "Thus, overexpression of FGF4 observed in our French bulldog population might merely be a breed-associated variant rather than a feature of their HGO, or it might be possible that this difference in genetic background contributes to more aggressive tumor behavior in dogs that develop HGO." (PMID 42135822, 2025). "In particular, in MDA-MB-231 and MRC5 cells, SR and CBD affect the secretion of growth factors involved in proliferation and angiogenesis (bFGF, FGF4, -6, -7, VEGF-D, PIGF, PDGF-AB, and -BB), tumor metabolism (IGFII, IGBPs), and immune response (GCSF, MCSF, TGF family members)." (PMID 37686233, 2023). "When implanted SC, EF43.fgf4 tumors grow rapidly (doubling-time ~19 h; see Section 2) and are highly infiltrated by macrophages, rendering them a well-suited model for MRI of TAM and tumor inflammation." (PMID 34359704, 2021).
tumor (continued). "Of the 10 mice injected with cells with FGF4 stimulation, two showed lung metastasis, two showed intravascular thrombus and three showed tumor invasion into skeletal muscle, whereas no metastasis sites were detected in mice injected with control cells and cells with FGF4+BHQ treatment." (PMID 27677589, 2016). "With a standard cell binding assay, we found that the peptides CRGFVVGRC, CQRALMIAC, and CRYSAARSC bound to EF43.fgf4 cells, whereas the peptide CSSTRESAC did not, indicating that CSSTRESAC might indeed recognize non-malignant stromal cells within the tumor microenvironment." (PMID 34060472, 2021).
cancer (34 papers, 2008 to 2025). A tumor composed of atypical neoplastic, often pleomorphic cells that invade other tissues. "In the resectable cohort, RANTES, TIMP-1, FGF-4, and IL-10 individually differentiated patients according to their cancer-associated survival." (PMID 36497475, 2022). "Two of the individual CTCs (CTC1 and CTC2) and the CTC pool had homogenous copy-number profiles, and included amplification on 1q and 8q (MYC), 11q (CCND1, FGF3, FGF4) and allelic loss of regions including several cancer genes on 3p (BAP1), 13q(RB1, BRCA2) and 17p (MAP2K4)." (PMID 36088510, 2022). "Previous research has shown that overexpression of FGF4 in fibroblast mixed cancer stem-like cells isolated from OC increases their sphere-forming capacity, however, knockdown of FGF4 can abrogate it." (PMID 38786089, 2024). "In the cancer setting, tumor-associated ECs were found to express IGFBP7 which stimulates IGF1 receptors on cancer cells thereby activating an FGF4 signaling loop that contributes to chemoresistance." (PMID 37060495, 2023). "Due to preferential binding of FGF2 and FGF4 to the IIIc-isoforms of FGFRs, the cancer cells expressing IIIc isoforms of FGFRs become sensitive to FGF2 and FGF4, which are abundant in stromal tissues." (PMID 36140527, 2022). "A Kaplan-Meier plotter was used to determine the prognostic value of the FGF4 gene by combining gene expression and cancer patient survival." (PMID 35888106, 2022). "We also evaluated the FGF4 against different types of cancer using the Kaplan-Meier bioinformatics analyses." (PMID 35888106, 2022). "Cancer-associated death was significantly longer in subjects with low levels of RANTES, TIMP-1, and FGF-4 (p = 0.002, p = 0.014 and p = 0.028, respectively)." (PMID 36497475, 2022). "For example, CAFs secrete epidermal growth factor (EGF), insulin-like growth factor 2 (IGF2), and fibroblast growth factor 4 (FGF4), which increase not only the proliferation but also the survival of cancer cells after irradiation." (PMID 34135469, 2021). "Except for altering the expression of differentiation proteins, FGF4 can induce cancer cells to be more mesenchymal-like and enhance their proliferation, invasion/migration, and colony initiation abilities." (PMID 27677589, 2016). "FGF4 is shown to play a key role in maintaining self-renewal capacity of normal and cancer stem cells." (PMID 27259269, 2016). "FGF‐4 promotes the tumorigenicity of cancer stem cells, and including FGF‐4 in the medium could enhance organoid formation after passaging." (PMID 37776168, 2023). "Unlike the other FGF family, the Fibroblast Growth Factor 4 (FGF4) gene does not increase the incidence of cancer, however, it has been reported to be associated with poor prognosis in multiple cancer types." (PMID 35888106, 2022). "FGF4 expression in these cancer stem cells increased sphere-formation, which could be reduced by silencing of FGFR2." (PMID 34068954, 2021). "Moreover, such diversity in signaling pathways can be seen in FGF4-related cancer pathology." (PMID 39766329, 2024). "Most of CEDGs like CCND1, ALDH3B1, MYEOV were frequently hypomethylated in cancer, while FGF3, FGF4, MRGPRF and CPT1A were hypermethylated in most cancers." (PMID 40478912, 2025). "These examples are GNRHR, FGF4, and FGF6, which have all been shown to play important roles in cancer biology." (PMID 38555407, 2024). "The co-amplification of FGF3, FGF4, FGF19, and CCND1was also observed in another pan-cancer study from the United States." (PMID 35494043, 2022). "Amplification of the 11q13 amplicon, present in breast cancer, results in co-amplification of FGF3, FGF4 and FGF19, but is also observed in other cancer types." (PMID 34068954, 2021). "In the presence of CAFs, expression of FGF4 and FGFR2 is increased in cancer stem cells isolated from the ovarian cancer cell line HTBoA." (PMID 34068954, 2021).